LINC01343 (long independently transcribed non-coding RNA 1343)
Gene: Long non-coding RNA gene on chromosome 1 (38,209,034 to 38,214,806, reverse strand). Ensembl gene ENSG00000237290.
Diseases named in the same sentence as LINC01343 in open-access papers:
LINC01343 is named in the same sentence as 6 diseases in open-access papers, as found by Europe PMC text mining. Sharing a sentence is not in itself a finding about the gene and the disease. The quoted sentences say what the papers report.
coronary artery disease (1 paper, 2022). "LINC01343 has been shown to be associated with type 2 diabetes (T2D) and coronary artery disease (CARD)." (PMID 36160032, 2022).
Ewing sarcoma (1 paper, 2023). A small round cell tumor that lacks morphologic, immunohistochemical, and electron microscopic evidence of neuroectodermal differentiation. "Previous studies have reported that LINC01343 expression is altered in Ewing’s sarcoma and oral squamous cell carcinoma." (PMID 37828032, 2023).
tumor (2 papers, 2022 to 2023). "The results show that the knockdown of LINC01343 suppressed tumor volume." (PMID 37828032, 2023). "An in vivo study further validated that LINC01343-knockdown repressed tumor growth." (PMID 37828032, 2023). "LINC01343 expression was 3.6-fold higher in HCC tissues than in the adjacent non-tumor tissues." (PMID 37828032, 2023). "In addition, the role of LINC01343 in the growth of tumors was verified using an in vivo xenograft tumor assay." (PMID 37828032, 2023). "Last but not least, our analyses indicated the high expression of CCDC18-AS1 and LINC01343 in BC at stages II-III and III, suggesting that the dysregulation of these factors may play a role implicated in both tumor invasion and metastasis." (PMID 36160032, 2022).
cancer (1 paper, 2022). A tumor composed of atypical neoplastic, often pleomorphic cells that invade other tissues. "In addition, a significant elevation of CCDC18-AS1 and LINC01343 expression was observed in the cancer tissues as compared to control groups (p < 0.0001 and p=0.0002, respectively)." (PMID 36160032, 2022). "In other words, we identified higher expression of 2.366-fold of SFN (|LogFC| = 1.243), 12.915-fold of LINC01343 (|logFC| = 3.691), and 10.584-fold of CCDC18-AS1 (|logFC| = 3.397) in the cancer tissue in comparison to the control group." (PMID 36160032, 2022). "Therefore, for future studies, investigating the exact molecular pathways of SFN, CCDC18-AS1, and LINC01343 in cancer may shed new light on the important and emerging role and function of these factors in tumorigenesis and lead to newer approaches for both the diagnosis and treatment of BC." (PMID 36160032, 2022).
LINC01343 also shares sentences with these, for which no sentence is quoted: breast carcinoma (1 paper); oral squamous cell carcinoma (1).